MTHFD2L (methylenetetrahydrofolate dehydrogenase (NADP+ dependent) 2 like)
Description:
Bifunctional mitochondrial folate-interconverting enzyme that has both NAD/NADP-dependent methylenetetrahydrofolate dehydrogenase and methenyltetrahydrofolate cyclohydrolase activities.
Synonyms: MGC72244
Tractability: Small molecule: a structure with a bound ligand is known. Antibody: UniProt places it where antibodies can reach, with medium confidence. PROTAC: ubiquitination databases record sites on it.
Target class: Enzyme; Oxidoreductase
Chemical probes: TH9619 (high quality)
Gene: Protein-coding gene on chromosome 4 (74,114,174 to 74,303,099, forward strand). Ensembl gene ENSG00000163738.
Subcellular location: Mitochondrion inner membrane
Pathways (Reactome):
Metabolism: Metabolism of folate and pterines
Gene Ontology:
Molecular function: protein binding; methenyltetrahydrofolate cyclohydrolase activity; methylenetetrahydrofolate dehydrogenase (NAD+) activity; methylenetetrahydrofolate dehydrogenase (NADP+) activity; catalytic activity
Biological process: folic acid metabolic process; tetrahydrofolate interconversion
Cellular component: mitochondrion; mitochondrial inner membrane; mitochondrial matrix
Genetic constraint (gnomAD): Loss-of-function variants: 21 observed, 25.42 expected, observed/expected ratio (o/e) 0.83, 90% interval 0.58 to 1.19. The upper end of that interval is the gene's LOEUF score, 1.19, which puts it in group 5 of 6, group 1 being the genes least tolerant of losing a copy. Missense variants: 419 observed, 372.74 expected, observed/expected ratio (o/e) 1.12, 90% interval 1.04 to 1.22. Synonymous variants: 150 observed, 133.98 expected, observed/expected ratio (o/e) 1.12, 90% interval 0.98 to 1.28.
Homologues: Orthologues: chimpanzee MTHFD2L (99% identical), macaque MTHFD2L (96% identical), pig MTHFD2L (88% identical), rabbit MTHFD2L (88% identical), mouse Mthfd2l (87% identical), rat Mthfd2l (86% identical), tropical clawed frog mthfd2l (71% identical), zebrafish mthfd2l (58% identical), Drosophila melanogaster Nmdmc (46% identical). Paralogues in human: MTHFD2 (65% identical), MTHFD1 (34% identical), MTHFD1L (20% identical).
Diseases named in the same sentence as MTHFD2L in open-access papers:
MTHFD2L is named in the same sentence as 8 diseases in open-access papers, as found by Europe PMC text mining. Sharing a sentence is not in itself a finding about the gene and the disease. The quoted sentences say what the papers report.
gastric cancer (1 paper, 2023). A primary or metastatic malignant neoplasm involving the stomach. "Rescue experiments confirmed that the circular RNA MTHFD2L played a role in inhibiting gastric cancer by coding the CM-248aa protein." (PMID 37829278, 2023).
cancer (9 papers, 2015 to 2025). A tumor composed of atypical neoplastic, often pleomorphic cells that invade other tissues. "Would it then be preferable to specifically target MTHFD2, which is strongly expressed in cancer cells, while sparing the MTHFD2L isozyme?" (PMID 41303507, 2025). "The widespread reactivation of MTHFD2 in tumors suggests an isoform switch from MTHFD2L to MTHFD2 during cancer transformation." (PMID 35228749, 2022). "Other genes involved in one-carbon metabolism were found transcriptionally repressed in HCC tissue, although the methylation pattern was unchanged in BHMT1, BHMT2, CBS, GNMT, and MTHFD2L in cancer as compared to cancer-free tissue or decreased in FOLH1." (PMID 25945129, 2015). "Another possibility is that, besides increased cytosolic flux, cancer cells could also utilize enhanced MTHFD2L activity to compensate for the inhibition of MTHFD2." (PMID 41303507, 2025). "In this context, MTHFD2, which is rarely expressed in normal adult tissues, where it has a functional substitute in MTHFD2L, may well be a safe therapeutic target for cancer treatment." (PMID 33782411, 2021). "MTHFD2L is thus likely a housekeeping gene allowing a baseline of mitochondrial 1C folate flux, with isozyme switching to MTHFD2 occurring in many cancers." (PMID 41303507, 2025). "Similarly, both isoenzymes are expressed in cancer cells, although MTHFD2 is highly upregulated in a wide range of tumors, in contrast to MTHFD2L." (PMID 40604332, 2024). "It has been proposed that MTHFD2L functions to maintain a baseline activity of mitochondrial folate metabolism, while MTHFD2 is upregulated in conditions where greater flux through the pathway is required, such as during embryogenesis or in cancer cells." (PMID 35712863, 2022). "Challengingly, they also demonstrated strong inhibition of the MTHFD1 and MTHFD2L isoforms, which are expressed in healthy adult human tissues, unlike MTHFD2 that is explicitly expressed in several cancer cells." (PMID 39256448, 2024). "Subsequent investigations found that although MTHFD2L is also found in cancer cells, it is expressed at much lower levels than MTHFD2, does not show the same pattern of pronounced upregulation in cancer cells, and is additionally not responsive to growth factors." (PMID 41303507, 2025).
tumor (3 papers, 2021 to 2024). "Results showed that the expression of five parent gene (PRIM2, ABCC4, UTRN, ABHD2, and MTHFD2L) was also significant increase in tumor compared to those in normal tissues." (PMID 34852706, 2021). "As a result of tumor immunity analysis, MTHFD2L expression was found to be negatively related to the Estimate-Stromal-Immune score in OSCC; however, there was no statistical significance between the Estimate-Stromal-Immune score and MTHFD1, MTHFD1L, or MTHFD2 in OSCC." (PMID 35693982, 2022).
MTHFD2L also shares sentences with these, for which no sentence is quoted: alcoholic liver diseases (1 paper); dyslipidemias (1); Fanconi anemia (1); nasopharyngeal carcinoma (1); uterine cancer (1).